STAT6 (signal transducer and activator of transcription 6)
Diseases named in the same sentence as STAT6 in open-access papers (continued):
Sharing a sentence is not in itself a finding about the gene and the disease.
cancer (continued). "On the other hand, IL-13 and IL-4 produced aberrant activation of STAT6, which boosts pro-metastatic activity in cancer cells such as invasion, migration, survival, and proliferation." (PMID 38419894, 2024). "STAT6 overexpression, detected in the immune microenvironment of cancer, promotes immunosuppression and metastasis formation by promoting angiogenesis." (PMID 38662084, 2024). "Some studies suggested that SND1 plays important roles in cancer by interacting with other transcription factors, including PPARγ, signal transducer and activator of transcription 5/6 (STAT6/5) and myeloblastosis oncogene (c-Myb)." (PMID 39436790, 2024). "The fusion of two genes on chromosome 12 – NAB2 and STAT6 – has been found in a rare form of cancer, known as a solitary fibrous tumor, which can form in almost any part of the body." (PMID 39370970, 2024). "Our study sheds light on the potential of STAT6 as a druggable target for CRC cancers, the findings offer hope for more effective treatments for CRC patients, especially those with advanced stages that are resistant to conventional therapies." (PMID 38419894, 2024). "Recent studies have reported STAT1 and STAT6 as regulators of proinflammatory and anti‐inflammatory microglial phenotypes in cancer." (PMID 39107960, 2024). "More importantly, it is clear that other STAT family members—STAT1, STAT2, STAT4, and STAT6—also contribute critical roles to cancer progression, either modulating the cancer cell directly or by altering cells of the TME." (PMID 37173951, 2023). "Signal transducer and activator of transcription 6 (STAT6) is a crucial macrophage M2 transcriptional program regulator in various cancer conditions." (PMID 37670933, 2023). "This was accompanied by reduced F4/80 mRNA expression and M2 macrophage markers in tumor tissues, demonstrating that inhibition of STAT6 had potential therapeutic implications for cancer therapy." (PMID 37173951, 2023). "Nevertheless, several studies have demonstrated anti-cancer activity of leflunomide through the suppression of STAT6 signaling." (PMID 37173951, 2023). "A recent study reported that STAT6 is involved in various human diseases, through its impacts on cell differentiation, cytokine production, and cancer development and progression." (PMID 34861103, 2022). "Chougule and coworkers formulated a gelatin-based nanocarrier formulation for delivery of a specific RNA called STAT6 siRNA to A459 cancer cells to inhibit the development and expression of STAT6 gene." (PMID 36011281, 2022). "STAT6 plays a role in tumorigenesis, immunosuppression, proliferation, and metastasis of human cancers." (PMID 35244291, 2022). "STAT6 is a key regulator of the macrophage M2 transcriptional program in various pathological conditions, including cancer." (PMID 35179953, 2022). "Regulatory T (Treg) cells play a major role in coordinating immunomodulation in cancer; however, the role of STAT6 in the induction and function of Treg cells is poorly understood." (PMID 33919941, 2021). "Signal transduction and transcriptional activator-6 (STAT6) is highly expressed in various human cancers." (PMID 34651050, 2021). "This suggests a critical role of STAT6 in immune-mediated cancer progression, and it can thus be considered a promising drug target or biomarker for BC prevention and/or treatment." (PMID 34572592, 2021). "PD-L1+ T cells suppress neighboring effector T cells via the PD-L1/PD-1 axis and promote STAT6-dependent, M2-like tolerogenic macrophages in cancer." (PMID 33320839, 2021). "For example, YTHDF1 expression had a strong association with STAT1 in Th1 cells, STAT6 in Th2 cells, STAT3 in Th17 cells, STAT5B in Treg cells, BCL6 in Tfh cells, and IRF5 in M1 macrophages in most cancer types." (PMID 34026603, 2021).
cancer (continued). "More directly, our findings provided evidence that the expression of DKK1 was correlated with the level of Th1 markers (STAT1 and IFNG) and Th2 markers (GATA3 and STAT6) in various cancers, such as ACC, KICH, MESO, and PAAD." (PMID 34899842, 2021). "STAT6 is an important factor in the activation of the monocyte population that participates in cancer development and progression." (PMID 32244885, 2020). "Immunostaining of candidate proteins MAX, TCF7L2, YY1, IRF1, STAT6, SP1, and E2F1 (selected based on qPCR results and/or associations to cancer in general) was performed in additional FTC specimens as outlined in the “Materials and Methods” section." (PMID 33063251, 2020). "In this study, the potential effects of four proprietary STAT6 siRNA sequences, previously tested for asthma treatment, were examined in the human cancer cell lines HT-29 and ZR-75-1." (PMID 31075146, 2019). "The results suggest that cancer cells inhibit CD11b+ cell proliferation in bone marrow and spleen cells derived from STAT6−/− mice." (PMID 31798581, 2019). "Equal numbers of CD11b+ cells were isolated from the bone marrow of WT and STAT6−/−mice and cocultured with cancer cells (LLC1 and A549) in Transwell plates." (PMID 31798581, 2019). "To further investigate the mechanism underlying the effect of STAT6 deficiency on the polarization of M1/M2 in the TME, we cocultured LLC1 cancer cells with CD11b+ cells derived from the bone marrow of either WT or STAT6−/− mice." (PMID 31798581, 2019). "STAT6 in CD11b+ cells increases IL-4 secretion, which in turn increases M2 myeloid cells and promotes cancer cell proliferation." (PMID 31798581, 2019). "The same phenomenon was observed in a coculture of cancer cells with spleen cells derived from either STAT6−/− or WT mice." (PMID 31798581, 2019). "Several studies have shown that STAT6 plays an important role in the progression and proliferation of several different types of cancer." (PMID 31075146, 2019). "Remarkably, D1 not only blocked IL-13 binding to IL13Rα2, but also inhibited IL13Rα1-mediated STAT6 activation in both cancer types." (PMID 30318506, 2018). "Based on the results, we found that STAT6, a cancer-related TF, regulated FOS and FOSB, while FOS and EGR1 were coregulated by 2 cancer-related TFs, including BRCA1 and SP1, respectively." (PMID 30228980, 2018). "Activation of GITR by its ligand enhances IL-9 expression in a STAT6- and NF-κB-dependent manner, followed by anti-cancer immune responses." (PMID 27832300, 2017). "STAT6 proteins that relay signals from activated cytokine in the plasma membrane to the nucleus, where they regulate gene transcription in the control of cancer growth." (PMID 26993600, 2016). "IL-4-induced STAT6 signaling is active in a variety of cell types, including immune cells and cancer cells, and plays an important role in the regulation of gene expression." (PMID 25333330, 2015). "From the MSigDB Cancer Neighbourhood Ontology, we found that the GM-enriched binding windows were in proximity to cancer-associated genes, CD53, VAV1, INPP5D, STAT6, HLA-C, etc." (PMID 25522020, 2014). "Recently, we found that platinum-based chemotherapeutic drugs that form the cornerstone in the medical treatment of many cancers, dephosphorylate STAT6, resulting in downregulation of PD-L2 by DCs." (PMID 22611421, 2012). "Compared with other STAT family members, the involvement of STAT6 in human cancer has received limited attention." (PMID 21595984, 2011). "The results described here support other works advocating an increasingly complex regulatory role for STAT6 in the context of cancer." (PMID 21595984, 2011). "STAT6 and IL-4 receptor (IL4R) expression in human HCC TAMs, along with the identification of a STAT6-related transcriptional signature associated with poor prognosis in HCC and other cancers, supports the rationale for clinical development." (PMID 41155971, 2025).
cancer (continued). "Therefore, STAT6 can be identified as a key regulator of cancer cell migration, including CRC cell migration." (PMID 38419894, 2024). "Future research on the molecular consequences of the fusion of NAB2 and STAT6 may help refine cancer diagnosis and inform drug development." (PMID 39370970, 2024). "Besides, in various malignancies, STAT6 function has been demonstrated to be critical in preserving the stemness properties of cancer cells." (PMID 38419894, 2024). "In this study, we hypothesized that 23-HBA could modulate STAT6 signaling to inhibit M2 macrophage polarization and further influence the response of cancer cells to 5-FU chemotherapy." (PMID 38554148, 2024). "In this type of cancer, 2-AG promoted the maturation of DC phenotypes and the production of pro-inflammatory cytokines through up-regulation of the signal transducer and activator of transcription 6 (p-STAT6)." (PMID 38074691, 2023). "In addition, the relation between HSP90 and activation of STAT3, STAT5 and STAT6 have been reported in preclinical cancer studies, further supporting our findings." (PMID 38274815, 2023). "In addition, the distribution of STAT1, STAT2, STAT3, STAT4, STAT5A, STAT5B, and STAT6 expression in CD8+ T cells in pan-cancer were displayed, which presented that STAT1 and STAT2 had prominent up-regulation in CD8+ T cell with ISG IFIT1." (PMID 36968603, 2023). "Collectively, these data indicate that STAT6 has potential for cancer therapy." (PMID 37173951, 2023). "In fact, STAT6 expression is also positively and negatively involved in cancer progression." (PMID 36061145, 2022). "The STAT6 transcription factor was chosen for these studies because it is a key regulator of the macrophage M2 transcriptional program in the TME in several human cancers." (PMID 35179953, 2022). "Moreover, only STAT6 showed significantly higher expression (p < 0.05) in epithelial samples of most cancer types." (PMID 35096592, 2021). "In some cancers, the activation of STAT6 is highly related to the increase of apoptosis inhibition, therefore, blocking the phosphorylation of this protein may be a mechanism triggered by Trimethylglycine to improve the response to 5-FU therapy." (PMID 32244885, 2020). "Its direct target STAT6 (signal transducer and activator of transcription-6) influences the over-expression of Bcl-xL (B-cell lymphoma-extra-large), which is responsible for cancer progression." (PMID 32102477, 2020). "Our study agreed with this report, as higher serum IL-13 and polymorphism at STAT6 rs167769 were reported to be the strongest variables associated with cancer progression in NASH patients, regardless of their fibrosis stages." (PMID 32283835, 2020). "Previous reports indicate that STAT6 plays a role in macrophage polarization that could lead to carcinogenesis and cancer progression." (PMID 32244885, 2020). "In this study, the effects of STAT6 siRNA over a longer period of time (7 and 14 days) were also investigated and this provided new data regarding the effects of STAT6 silencing on cell proliferation and apoptosis in cancer cells." (PMID 31075146, 2019). "Considering the critical negative regulatory role of M2-prone TAMs in regulating antitumor immunity, the study of Stat6 transcriptional modulation may promote the identification of therapeutic targets for cancer immunotherapy." (PMID 31554795, 2019). "Interestingly, a marked reduction in the percentage of CD11b+ cells was observed in bone marrow cells derived from STAT6−/− mice compared to bone marrow cells from WT in the cocultures with cancer cells." (PMID 31798581, 2019).
cancer (continued). "Accordingly, drugs that restore STAT6 expression, such as 5-Aza, may be useful for cancer therapy in combination with rapamycin." (PMID 31530290, 2019). "In addition, mesenchymal markers, invasiveness related enzymes, angiogenesis-related proteins, and the cancer stem-like cell marker proteins were upregulated by activating the JNK/β-catenin/Stat6 signaling axis in metastatic pulmonary tissues." (PMID 27895317, 2016). "IL-4 also promotes migration of cancer cells via the Akt/Stat6 pathway signaling." (PMID 27895317, 2016). "However, over the last decades, the elevated expression of STAT6 was found in various cancers." (PMID 39936166, 2025). "In addition, previous studies have demonstrated that depletion of wild-type STAT6 may elicit beneficial effects in cancer therapeutics via inhibition of M2 macrophage differentiation." (PMID 38511173, 2024). "MiR23a and MiR27a suppress Jak1/Stat6 and Irf4/Ppar-γ of the Jak1/Stat6 pathway, respectively, again supporting how the Mir-23-27-24 clusters adopt a double-negative feedback loop in macrophage polarization networks, further providing evidence of their key regulatory activity in cancer progression." (PMID 38871817, 2024). "Additionally, the distribution of STAT1, STAT2, STAT3, STAT4, STAT5A, STAT5B, and STAT6 expression in CD4+ T cells in pan-cancer were also clearly illustrated, which showed that STAT1 and STAT2 expression were notably up-regulated in CD4+ Treg cell with marker OSA1 and CD4+ T cell with ISG IFIT1." (PMID 36968603, 2023). "Recent studies have shown that STAT6 signaling reduces cancerous growth and/or metastasis in solid tumors of the gastrointestinal tract, the breast, the lung, and the prostate, suggesting that STAT6 signaling could prevent these cancers." (PMID 36176415, 2022). "Thus, techniques aimed at reducing or blocking STAT6 expression may be useful in treating STAT6high cancers." (PMID 31075146, 2019). "This may be due to the fact that the apoptosis assay was analyzed after 7 days post-transfection, which would allow the STAT6 pathway to complete its action mechanism, or that the STAT6 siRNA sequences are more powerful at inducing the apoptosis of the cancer cells." (PMID 31075146, 2019). "Moreover, USP17 promoter region analysis revealed different transcription factor binding sites, including those for transcription factors HIF-1, STAT3, STAT6, and NF-κB, which are known to be activated on stimulating cancer cells by cytokines in a cross talk between TAMs and cancer cells." (PMID 30038267, 2018). "Since STAT6 can act as either pro-or antiapoptotic factor depending on the cell type a key pending question is whether STAT6 siRNA may have therapeutic activity in cancer." (PMID 22162773, 2011). "Lanatoside C, a cardiac glycoside, has been shown to induce apoptosis in cancer cells by suppressing the Janus kinase (JAK)/signal transducer and activator of transcription (STAT)/cytokine signaling (SOCS) (JAK2/STAT6/SOCS2) pathway." (PMID 38527038, 2024). "RAB1A overexpression promotes cancer cell migration, invasion, and metastasis by activating JAK1/STAT6 signaling." (PMID 37370041, 2023). "Among the STAT family proteins, STAT1 to STAT6, it was revealed that STAT3 functionally plays an important role in manipulating the biological activities of cancer cells, by affecting their energy metabolism, that is, the metabolism of glucose and lipids." (PMID 36899895, 2023). "Signal transducer and activator of transcription 6 (STAT6) is overexpressed in various human cancers, and is a regulator involved in multiple biological processes of cancers." (PMID 33006365, 2020). "Surprisingly, this study sheds light on the possible integration of IL-13/STAT6 axis and Hippo signaling through YAP1 in cancer progression in NASH." (PMID 32283835, 2020). "Therefore, techniques aimed at reducing STAT6 expression may be useful in treating those cancers." (PMID 31075146, 2019).
cancer (continued). "Equal numbers of CD11b+ cells were isolated from the bone marrow of WT and STAT6−/− mice and mixed with 1 × 106 LLC1 cancer cells and inoculated subcutaneously into nude mice." (PMID 31798581, 2019). "Treatment of KPC1242 cancer cells with DMXAA, alone or in combination with gemcitabine, increased phosphorylation of TBK1 and STAT6, two cardinal STING signaling pathways." (PMID 31036082, 2019). "Due to their oncogenic potential STAT3, STAT5, and STAT6 are attractive targets for therapeutic intervention and STAT inhibitors are in development as anti-cancer drugs." (PMID 28903353, 2017). "CCL17 is a known STAT6 transcriptional target and chemoattractant that recruits various CCR4 + immune cells—such as CD8+ or CD4+ T-cells, and macrophages—in murine and canine cancer models, in addition to human tumors." (PMID 38285120, 2024). "Additionally, STAT1 and STAT6 also play a role in metabolism as STAT1, STAT3, STAT5, and STAT6 each play a role in the creation of a dynamic metabolism within cancer cells." (PMID 38464736, 2024). "Most of the activated TFs are involved in cancer progression through the TIME, such as the NFκB family (NFKB1, NFKBIA, and RELA) and the STAT family (STAT1, STAT2, and STAT6), which are critical in M1 and M2 macrophage polarization." (PMID 36230879, 2022). "High expression of STAT6 has been detected in many types of cancer, including non-small-cell lung cancer and colorectal cancer." (PMID 35600336, 2022). "The positive cells of senescence-associated β-galactosidase staining and cGAS, STING, interferon-regulatory factor 3 (IRF3), and signal transducer and activator of transcription 6 (STAT6) expression levels using immunostaining were elevated in HGD and in cancers." (PMID 36061145, 2022). "We identified genes for which ASEs were observed in both the Afro-Caribbean cohort and the Jurkat cells expressing Tax or HBZ, including cancer genes EIF4A2, IKBKB, LZTR1, STAT6 (for Tax); CARS, MDM2, IKZF1 (for HBZ); and EWSR1, MUTYH, and PTPRC (for both Tax and HBZ)." (PMID 34543356, 2021). "Some studies showed that the induction of miR-135a expression in different types of cancers could suppress cell proliferation through target genes (c-MYC, STAT6, SMAD5, and BMPR2)." (PMID 34377051, 2021). "However, the contribution of IL-13/STAT6 and YAP1, together with serum AFP, are proven to have the upper hand in predicting cancer development in NASH." (PMID 32283835, 2020). "Of these, the average expression of the two genes, including CD70 and PDCD1, and the 12 isoforms derived from the seven genes, including CD40, CD70, IL6, IL10, STAT1, STAT6, and TNFRSF14, were cancer immunotherapy-related genes (false discovery rate (FDR) < 0.01)." (PMID 31292525, 2019). "To investigate whether STAT6 directly activated GATA3, we overexpressed STAT6 in various cancer cells and observed the upregulation of GATA3 expression." (PMID 30218063, 2018). "When ECP is used to treat immune-related adverse events in cancer patients due to treatment with immune checkpoint inhibitors, the apoptotic leukocytes induced by ECP are ingested by intestinal macrophages leading to an anti-inflammatory M2-like polarization of macrophages by STAT6 signaling." (PMID 40881697, 2025). "Indeed, we discovered that 23-HBA decreased the phosphorylation level of STAT6 protein in M2 macrophages, accompanied by a decrease in M2-related cytokine IL-10 secretion and an inhibition of STAT3/Bcl-2 signaling of cancer cells, resulting in a reduction in 5-FU resistance." (PMID 38554148, 2024). "Importantly, depleting STAT6 expression in macrophages abolished the suppressive effect of 23-HBA on M2 macrophage polarization, while also eliminating its ability to decrease M2 macrophage-induced 5-FU resistance in cancer cells." (PMID 38554148, 2024). "In addition, using an independent cohort from BC Cancer, where phospho-STAT6 histology data was not available, CCL17 expression was compared in STAT6WT and STAT6D419 mutant patient samples." (PMID 38285120, 2024).